IL10 (interleukin 10)
Diseases named in the same sentence as IL10 in open-access papers (continued):
Sharing a sentence is not in itself a finding about the gene and the disease.
COVID-19 (continued). "COVID-19 has been associated with an exuberant activation of the host immune system and the excessive production of proinflammatory cytokines, such as IL-1, IL-2, IL-6, IL-10, IL-12, IFN-γ, TNF-α, among others, which may cause tissue injury, particularly on the lungs." (PMID 35090394, 2022). "This assumption is confirmed not only by significant higher serum value of IL-10 in stage III of COVID-19 patients compared to stage I and II, but more importantly, by strong positive correlation that persists between Gal-1 and IL-10." (PMID 35075140, 2022). "So, the current study evaluated the cardiac biomarkers and expression analysis of IL-1, IL-6, IL-10, IL-17 and IL-25 among COVID-19 patients from Pakistan." (PMID 36298704, 2022). "SARS-CoV-2 appears to downregulate the expression of ACE-2 on peripheral blood monocytes which show an activated phenotype in COVID-19 evidenced by morphology and IL-6, IL-10, and TNF-α production." (PMID 35913134, 2022). "While IFN-α and IFN-β were undetectable, IL-10, IL-17A and IL-18 were variably detected in COVID-19 BALF, with higher RNA and/or protein levels of IL-6, MCP-1 and IL-33 and lower IL-6 receptor (IL-6R) observed in COVID-19 BALF compared to healthy BALF19,20." (PMID 35589689, 2022). "Our search covered published studies reporting laboratory parameters for T-cell subsets (CD4/CD8) and IL-10 among confirmed COVID-19 patients." (PMID 35572964, 2022). "In this study, we systematically analyzed the serum levels of IL-1β, IL-2, IL-4, IL-6, IL-8, and IL-10 in COVID-19 patients with different disease severities, as well as in healthy controls." (PMID 35540724, 2022). "We also detected immunoregulatory markers, such as IL-10, which was previously reported as a marker of COVID-19 severity, and soluble PD-L1 (sPD-L1), which binds to PD-1 on the surface of effector CD8 T cells promoting their suppression or exhaustion." (PMID 35479098, 2022). "In the present study, we showed that IL-10 is significantly increased after 2 weeks from symptoms onset in the plasma of COVID-19 patients likely acting as an internal control cytokine to block the over-expression of several endogenous immune factors." (PMID 36148228, 2022). "The network pharmacology showed CHM formulas affected several inflammation-related proteins for COVID-19, including IL-10, TNF-α, IL-6, TLR3, and IL-8, in which Dexamethasone and Aspirin covered only IL-10 and TNF-α." (PMID 35890093, 2022). "Within COVID-19 patients, serum IL-6 and IL-10 levels, which were found to be predictive of disease severity, are significantly higher in critical group than in moderate and severe group." (PMID 36406394, 2022). "This viremia and virus replication results in serious symptoms, one of which is the triggering of cytokine storms, including interferon-alpha, IL-2, IL-6, IL-10, and C-reactive protein, which can erode the health of COVID-19 patients." (PMID 35812166, 2022). "Supernatants were subsequently analyzed for key inflammatory cytokines associated with the cytokine storm in COVID-19 (IFN-γ, IL-1β, IL-2, IL-4, IL-6, IL-8, IL-10, IL-12p70, IL-13, and TNF-α), using the Meso Scale platform." (PMID 36296272, 2022). "Results of a cohort study showed that diminution of some bacterial species in patients with COVID-19 was connected to increase in the level of IL-10, TNF-α, CXCL10, and CCL2 and immunological responses." (PMID 35342407, 2022). "IL-10 was reported to contribute to the suppression of the immune system, viral control, and disease severity, and a predictor of poor outcomes in COVID-19 patients." (PMID 35529862, 2022). "Among COVID-19 patients, the most common disorders of cytokines and chemokines are increased levels of IL-1β, IL-2, IL-6, interleukin-7 (IL-7), IL-10, TNF-α, CRP, chemokine ligand 2 (CCL2), as well as an increase or decrease in the concentration of IFN-γ." (PMID 36294388, 2022).
COVID-19 (continued). "The ratios of IL-12/IL-4, IL-12/IL-10, IL-12/IL-5, IL-12/IL-9, IL-2/IL-10, and IL-2/IL-9 were substantially higher in COVID-19 ICU patients compared with HC subjects (≈5660-, 5333-, 2100-, 600-, 69-, and 24-fold differences, respectively)." (PMID 36363785, 2022). "A study conducted on COVID-19 patients, showed a significant increase in serum IL-10 levels in critical group (n = 17) than in moderate (n = 42) and severe (n = 43) group." (PMID 37521849, 2022). "Serum IP-10, MCP-1, CRP, IFNγ, IL-10, IL-13, IL-17α, IL-23, and IL-6 were significantly higher in COVID-19 patients compared to controls." (PMID 36554094, 2022). "IL-10 treatment induced a downregulation of the majority of analytes in COVID-19 and in NO COVID-19-VCs in a similar way." (PMID 36148228, 2022). "The results from these two mathematical models suggest the circulating marker IL-10 as a driving key marker for the stratification of COVID-19 patients according to disease severity." (PMID 35529862, 2022). "There were significant association between IL-1β & neutrophils (r = 0.42, p<0.05), IL-10 & WBC (r = 0.39, p<0.05), IL-10 & Basophils (r = -0.51, p<0.01), IL-17 & Neutrophil (r = 0.39, p<0.05) in the active COVID-19 cases." (PMID 36094915, 2022). "Receptors for type I (IFNAR1 and 2) and III (IL10RB) interferons drive inflammation mediated by NK and CD8+ T cells, and IL-10RB binds IL-10 whose levels are a severity predictor in COVID-19." (PMID 35659055, 2022). "Cytokine levels of IL-6 and IL-10, which are markedly increased in patients with COVID-19, can elicit the upregulation of NKG2A expression, potentializing its inhibitory role." (PMID 35806995, 2022). "A recent paper reported that elevated plasma levels of IL-6, IL-10 and IP-10 anticipated clinical progression of COVID-19 patients." (PMID 35563282, 2022). "Our results evidence that patients with COVID-19 residing in high-altitude tend to have higher levels of inflammatory cytokines, particularly IL-6, IL-10 and TNF-α." (PMID 35090394, 2022). "IL-10 is thought to contribute to disease pathogenesis in COVID-19 by either due to its action as an immunostimulatory molecule or because of inability to suppress the hyperinflammation state." (PMID 35786403, 2022). "A recent study reported that asymptomatic COVID-19 patients have a reduction in Tregs and anti-inflammatory cytokine IL-10." (PMID 35497875, 2022). "Baseline levels of several immune factors, including IL-10, were significantly elevated in COVID-19 patients compared with NO COVID-19 subjects in “study population A”." (PMID 36148228, 2022). "Although dramatic elevation of IL-10 and IL-6 with inflammatory markers such as C-reactive protein have been reported in severe or critical COVID-19 cases." (PMID 36094915, 2022). "The data from these two mathematical models suggest a panel of cytokines and biochemical markers for stratifying COVID-19 patients according to disease severity, with the circulating marker IL-10 as the driver key marker." (PMID 35529862, 2022). "IL-10 is mainly known as an anti-inflammatory cytokine and was shown to be a prognostic marker for poor outcome in COVID-19 patients." (PMID 36275812, 2022). "Our results indicated that serum levels of IL-2, IL-4, IL-6, and IL-10 were increased in COVID-19 patients compared to healthy subjects." (PMID 35540724, 2022). "Compared with those in mild disease, levels of inflammatory factors such as IL-2, IL-12 (p40), and IL-10 were increased in moderate disease, and these factors have been previously reported to be increased in patients with COVID-19." (PMID 35254122, 2022). "The integrated areas of the regions related to IFN-γ, TNF-α, IL-1 β, IL-6, and IL-10 were obtained to elucidate the quantity of those cytokines in the V-COVID-19 and V-Healthy groups." (PMID 36497139, 2022).
COVID-19 (continued). "This is similar to findings of positive regulation of genes encoding the activation of innate immune system, viral and IFN response, increase of proinflammatory macrophages and elevated IL-6 and IL-10 in severe COVID-19 cases." (PMID 35663963, 2022). "The importance of IL-6 and IL-10 as major pro- and antiinflammatory cytokines was shown in many trials on COVID-19 with meta-analyses showing the prevalent role of these two cytokines in disease severity and prognosis." (PMID 35887283, 2022). "Vitamin D has also been shown to increase the production of anti-inflammatory cytokines, such as IL-10, which is predicted to lower the severity of COVID-19, and improve the activity of macrophages and T lymphocytes." (PMID 35238285, 2022). "In fact, in our case, in mothers affected by COVID-19 we find an increase in IL-10 since it makes us understand how the maternal immune system is fighting the viral infection in defense of the fetus." (PMID 35408809, 2022). "Another important actor that deserves attention is IL-10, since elevated levels predict poor outcomes in patients with COVID-19." (PMID 35563218, 2022). "We then found that IL-10 at 5 ng/ml significantly downregulates spike-induced IFN-γ response in spike-responders of COVID-19 patients (14/29) [1.82 (0.30-3.468) vs 0.11 (0.37-0.75), p=0.0004] identified based on a cut-off previously defined." (PMID 36148228, 2022). "Many cytokines have been reported to be increased in severe COVID-19 patients and a few of them, such as IL-6, IL-8, IL-10 and TNF-α, are considered to be indicators of severe disease." (PMID 35337002, 2022). "As observed in this study and others, IL-6, IL-8 and IL-10 have systematically been reported as increased in COVID-19, particularly in the acute phase of the disease." (PMID 36077133, 2022). "It has been reported that monocytes appear to produce more tumor necrosis factor alpha (TNF-α) and interleukin-10 (IL-10) in COVID-19 patients." (PMID 35690714, 2022). "In the current study, IL-10 was significantly higher among patients with active COVID-19 conpared to the recovered patients and the unexposed controls." (PMID 36094915, 2022). "The levels of TNFa, IL-6, IL-1b, IFNg, IL-2, and IL-10 have been reported as inflammatory cytokines in COVID-19." (PMID 35669157, 2022). "Laboratory abnormalities observed in adults, including elevated levels of D-dimers and cytokines (IL-6, IL-10, TNF-alpha), have been associated with severe COVID-19 courses and increased mortality." (PMID 35546159, 2022). "Among the different antiviral cytokines, elevated levels of IL-10 and IL-6 are predictors of COVID-19 severity." (PMID 36440226, 2022). "This cytokine storm causes an increase in T-helper (Th)-1 cytokines, including TNF-α, IL-1β, CCL2, CXCL10, IL-6, and IFN-γ, and Th-2 cytokines, including IL-10, IL-4, and IL-1 receptor antagonists in the serum of COVID-19 patients." (PMID 35053059, 2022). "Patients with severe COVID-19 had higher IL-10 and lower CCL22 compared to the mild or moderate group." (PMID 35958594, 2022). "This systematic review and meta-analysis investigated the levels of T-cell subsets and IL-10 in COVID-19 patients." (PMID 35572964, 2022). "Symptomatic COVID-19 patients had significantly (p < 0.05) higher levels of IL-10, IL-2, IL-2R, IL-6, IL-8 GM-CSF IP-10, TNF-α, IL-4, IL-5, IL-12, IFN-γ and MIP-1β compared to the asymptomatic cases." (PMID 36184636, 2022). "In fact, the variations in the prevalence of COVID-19 and its mortality among countries is explained by the IL-10 rs1800896 SNP." (PMID 36233516, 2022). "In conclusion, besides the well-known inflammatory markers CRP and IL-6, a panel of other cytokines such as IP10, sIL2Rα and IL-10 appear as very interesting tools to stratify COVID-19 patients, deserving possible new strategic intervention." (PMID 35563218, 2022). "In the serum of severe COVID-19 patients, only anti-inflammatory cytokine IL-10 was significantly increased." (PMID 36585712, 2022).
COVID-19 (continued). "In parallel, the COVID-19 patients who died had significantly higher levels of soluble IL-10, an anti-inflammatory cytokine reported to inhibit ROS production by activated neutrophils." (PMID 35637483, 2022). "Serum levels of IP-10, CRP, IL-10, IFNγ, IL-13, IL-17α, IL-23, IL-6 were particularly upregulated in COVID-19 patients compared to controls." (PMID 36554094, 2022). "Within the second week, levels of IL-10 and GM-CSF were significantly higher compared with NO COVID-19 controls and remained elevated." (PMID 36148228, 2022). "Patients with COVID-19 had significantly higher CSF concentrations of neopterin, β2M, interleukin (IL) 2, IL-6, IL-10, and tumor necrosis factor α (TNF-α) compared with controls." (PMID 35604688, 2022). "In most studies, compared with healthy controls, COVID-19 patients had significantly higher levels of interleukin (IL)-2, IL-4, IL-6, IL-10, tumor necrosis factor (TNF)-α, and C-reactive protein (CRP) and lower lymphocyte counts." (PMID 35310853, 2022). "Further, on the one hand a repression of anti-inflammatory cytokines, such as IL-10, on the other hand an excessive secretion was described in critical COVID-19." (PMID 35860660, 2022). "In intergroup analysis, the COVID-19 groups showed higher salivary levels of IL-10, IL-13, IL-17A, and IFN-α than the control group." (PMID 35686128, 2022). "In this meta-analysis, we analyzed serum levels of IL-1β, IL-2, IL-4, IL-6, IL-8, and IL-10 in COVID-19 patients with different disease severities." (PMID 35540724, 2022). "Our investigation showed an increased concentration of IL-10 in COVID-19 patients with severe conditions compared to the healthy group (p = 0.0002) and patients with mild symptoms (p = 0.0005)." (PMID 35842705, 2022). "In conclusion, circulating miR-144-3p, possibly in combination with IL-10 or EGF, emerges as a noninvasive tool for early risk-based stratification and mortality prediction in COVID-19." (PMID 36414650, 2022). "Our results indicate in ex-vivo experiments that exogenous addition of IL-10 to whole-blood cells of COVID-19 patients reduces the SARS-CoV-2-specific immune response." (PMID 36148228, 2022). "We systematically searched records investigating the role of interleukins (IL-1β, IL-2, IL-4, IL-6, IL-8, and IL-10) in COVID-19 patients in Web of Science, Pubmed, and Embase through December 2020." (PMID 35540724, 2022). "Our data have shown that IL-10 levels were decreased in COVID-19 patients and even lower in patients progressing to death." (PMID 36451835, 2022). "COVID-19 is characterized by high levels of pro-inflammatory cytokines and chemokines, including IL-2, IL-7, IL-10, G-CSF, IP10, MIP-1A, MCP-1, and TNFα, especially in patients cared for in ICU." (PMID 36423162, 2022). "Three studies demonstrated a high proportion of CD14+ and CD16+ cells in patients with severe COVID-19, with inflammatory factors including GM-CSF and IL-6, IL-10 and TNF-α." (PMID 35843719, 2022). "A low number of Tregs and their factors FoxP3, IL-10, and TGF-β and inflammation can be regarded as the major causes of disease pathogenesis in patients with COVID-19." (PMID 36016311, 2022). "Similar to dengue, those who proceed to develop severe COVID-19 have high levels of many proinflammatory cytokines such as IL-6, IL-1β, IL-10, CXCL-10, MCP-1 and the cytokine storm is shown to associate with both severe dengue and COVID-19." (PMID 35786403, 2022). "IL-10 is considered as an anti-inflammatory cytokine but has also been found to be upregulated in COVID-19 patients 35-37." (PMID 35401811, 2022). "COVID-19 patients have high levels of pro-inflammatory cytokines and chemokines such as IL-1β, IL-2, IL-6, IL-7, IL-10, IFN-γ, TNF-α, G-CSF, CCL2, and CXCL10." (PMID 35782361, 2022). "Here we investigated the impact of IL-10 in COVID-19, through the ex-vivo assessment of the effects of exogenous IL-10 on SARS-CoV-2-specific-response using a whole-blood platform." (PMID 36148228, 2022).
COVID-19 (continued). "The chest CT image of COVID-19 patients showed ground-glass opacity, and compared with healthy adults, the plasma concentrations of IL-1β, IL-7, IL-8, IL-9, IL-10, IFN-γ, TNF-α, and VEGF of COVID-19 patients were all upregulated." (PMID 35874688, 2022). "In summary, we found that ICU admission levels of serum IL-10 and TNFα were useful and statistically powerful prognostic markers for clinical outcomes in severe COVID-19." (PMID 36451808, 2022). "Resistin was significantly associated with IL-6, IL-8, IL-10, VCAM-1 and ICAM-1 in the COVID-19 patients." (PMID 35784283, 2022). "All cytokine and chemokine levels except for IL-10 were higher in both of the groups of COVID-19-positive subjects compared with the levels in the healthy controls." (PMID 36294868, 2022). "The marked rise in plasma levels of the anti-inflammatory cytokine IL-10 in severe COVID-19 is an unexpected observation, however, a similar finding has been reported in adults with severe COVID-19." (PMID 35663467, 2022). "Taken together, these data suggest that although the ADO signaling pathway is compromised in COVID-19, this nucleotide can still trigger the production of IL-10 and partially suppress inflammatory responses." (PMID 36248842, 2022). "Systemic values of IL-1β (p = 0.001), IL-6 (p = 0.001), IL-10 (p = 0.026), IL-23 (p = 0.001), IL-33 (p = 0.001), and Gal-1 (p = 0.001) were significantly higher in COVID-19 patients in stage III compared to patients in stage I and II." (PMID 35075140, 2022). "Their results show a higher incidence of severe and even fatal forms of COVID-19 when IL-6 and IL-10 are high." (PMID 35874678, 2022). "Lymphocytopenia is negatively correlated with increased serum levels of tumor necrosis factor alpha (TNF-α), IL-6 and IL-10 and postmortem examinations of COVID-19 patients revealed lymphocyte depletion and spleen necrosis in parallel with lymphocyte death." (PMID 35453524, 2022). "It was established that serum concentrations of IL-10 were higher in severe COVID-19 patients compared to the recovered and control groups." (PMID 36232655, 2022). "Patients with severe COVID-19 had higher IL-10 and lower macrophage-derived chemokine (MDC, CCL22) compared to the mild or moderate group (P<0.05)." (PMID 35958594, 2022). "Among the inflammatory mediators, interleukin-6 (IL-6), interleukin-8 (IL-8), and interleukin-10 (IL-10) are higher in patients with COVID-19-related ARDS." (PMID 35327420, 2022). "Anti-inflammatory cytokine IL-10 was shown to be more strongly related with disease progression and severe acute kidney injury than the proinflammatory cytokines IL-6 and IL-8 in COVID-19 patients with severe sickness." (PMID 35958594, 2022). "The increased IL-10 concentration in the plasma sample of active COVID-19 cases indicates providing some form of protection to the infected individuals." (PMID 36094915, 2022). "Previous studies have also shown the potential role of IL-10 in COVID-19 pathogenesis and as predictor of severity." (PMID 36672534, 2022). "Specifically, elevated IL-6 and IL-10 levels observed in COVID-19, can inhibit NK cytotoxicity, mediated by Granzyme-B production, Fas/FasL (Fas ligand) interaction and CD16 binding with the Fc (constant fraction) of antibodies." (PMID 35336077, 2022). "Increased production of interleukins (IL-6, IL-10) and coagulopathy lead to high fatality rates in hospitalized COVID-19 patients." (PMID 36397967, 2022). "IL-10, another Th2 cytokine, exhibited significant correlation with CK-MB and troponin I in moderate COVID-19 patients and with serum creatinine, urea, CK-MB, and LDH in severe cases." (PMID 35891209, 2022). "A metanalysis carried out by Hu and colleagues have reported that while higher levels of IL-10 were higher in the severe or death COVID-19 subgroups." (PMID 36451835, 2022). "Prominent levels of CD25, IL-8,IL-9 and IL-10 were measured in B cells from peripheral blood of severe COVID-19 patients." (PMID 36211412, 2022).